CHD5 (chromodomain helicase DNA binding protein 5)
Diseases named in the same sentence as CHD5 in open-access papers (continued):
Sharing a sentence is not in itself a finding about the gene and the disease.
glioma (12 papers, 2009 to 2025). A benign or malignant brain and spinal cord tumor that arises from glial cells (astrocytes, oligodendrocytes, ependymal cells). "Then, we confirmed that the expression level of CHD5 was associated with tumor immune infiltration and tumor microenvironment, especially in glioma." (PMID 35955624, 2022). "In conclusion, CHD5 is a promising therapeutic target in cancer and is a prognostic marker that is associated with immune infiltration in glioma." (PMID 35955624, 2022). "In the pan-cancer survival analysis, although CHD5 expression was associated with the prognosis of various cancers, it appeared to be strongly associated with the prognosis of neurological tumors (Glioma, LGG, and NB)." (PMID 35955624, 2022). "Notably, the loss of CHD5 occurred frequently in the genome, which affected the copy number of CHD5 in glioma (Loss = 56, Gain = 5), and was one of the reasons for the low expression of CHD5 in Glioma." (PMID 35955624, 2022). "Kaplan-Meier analysis also showed that high CHD5 expression was significantly associated with increased DFI in Glioma (Figure A2B, p < 0.001), KIPAN (Figure A2C, p < 0.001), PAAD (Figure A2D, p < 0.01), KICH (Figure A2E, p = 0.02) and LGG (Figure A2F, p = 0.04)." (PMID 35955624, 2022). "In Glioma, up to 16 types of immune cells were associated with CHD5 expression." (PMID 35955624, 2022). "Additionally, CHD5 was found to be strongly associated with tumors of Glioma." (PMID 35955624, 2022). "In high-risk gliomas, recurrent CNVs—such as chromosome 7/12 amplifications (EGFR, CDK4/MDM2) and chromosome 1/8/13 deletions (CHD5, DLC1, RB1)—play pivotal roles in promoting proliferation, immune evasion, and DNA repair defects." (PMID 40636690, 2025). "The expression of CHD5 in Glioma was significantly negatively correlated with 5 types of immune cells, except B cells." (PMID 35955624, 2022). "Although bioinformatics analysis provided us with some important insights about the role of CHD5 in malignancies, we further validated the tumor suppressor role of CHD5 in glioma using molecular biology methods." (PMID 35955624, 2022). "Consistent with previous studies, the expression of CHD5 gene in Glioma was significantly negatively correlated with the 5 immune cells types, except B cells." (PMID 35955624, 2022). "The results showed that the expression of CHD5 was significantly positively correlated with the age in three tumor types, namely, Glioma (p = 0.02), KIRC (p = 0.03), and UCS (p = 0.03), and was significantly negatively correlated in MESO (p = 0.01)." (PMID 35955624, 2022). "In conclusion, the present study demonstrates that CHD5 expression affects glioma progression and migration." (PMID 35955624, 2022). "Univariate Cox analysis showed that CHD5 expression was associated with overall survival (p < 0.05) in BRCA, LAML, Glioma, KIPAN, NB, KICH, LGG, and PAAD." (PMID 35955624, 2022). "CHD5 was identified as a tumor suppressor gene, and it has been reported deregulated in glioma, colon, lung, ovarian, prostate and breast cancers." (PMID 29682202, 2018). "CHD5 methylation has been identified in several cancer types including glioma, breast, colon, lung, ovary and prostate cancers, suggesting the contribution of epigenetic regulation to its biallelic inactivation." (PMID 26943038, 2016). "CHD5 has been reported frequently methylated in multiple human cancers, including glioma, breast, lung, gastric, colon, ovarian and prostate cancers." (PMID 26943038, 2016). "Our findings, however, suggest that the role of CHD5 as a tumor suppressor in glial tumors needs further investigation." (PMID 20950435, 2010). "Moreover, si-RNA mediated knockdown of CHD5 promoted the proliferation and migration of glioma cells in vitro." (PMID 35955624, 2022).
glioma (continued). "Interestingly, in this study, we revealed the biological role of CHD5 in glioma cells, wherein we found that the knockdown of CHD5 enhanced the proliferation and migration of glioma cells in vitro." (PMID 35955624, 2022). "Furthermore, we explored the effect of CHD5 on glioma proliferation and migration using the cell counting kit 8 (CCK-8) assay, transwell assays and western blot analysis." (PMID 35955624, 2022). "In addition, DSS analysis showed that CHD5 expression was associated with the prognosis of BRCA, PRAD, COADREAD, Glioma, KICH, KIPAN, LGG and KIRP (p < 0.05) (Figure A1A)." (PMID 35955624, 2022). "CHD5 is expected to be a potential tumor prognostic marker, especially in glioma." (PMID 35955624, 2022). "Finally, we summarized and intersected the results from the analysis of these four prognostic data, and found that CHD5 showed strong prognostic correlation in CNS tumors, especially Glioma." (PMID 35955624, 2022). "Recently, the CHD5 promoter has been found to be methylated in small subsets of breast (4.4%), colon (10%), ovarian (15%) and glioma (17%) tumors, suggesting epigenetic silencing of CHD5 by methylation may play a partial role in tumorigenesis in these tissues." (PMID 19840376, 2009). "In addition, the TME, TMB, MSI, and immune infiltration might contribute to the dysregulation of CHD5 expression in cancer, and CHD5 may be a potential therapeutic target for glioma immunotherapy." (PMID 35955624, 2022). "Our results showed that CHD5 expression was positively correlated with the stromal scores in 18 types of cancers, was correlated with the immune scores in 19 types of cancers, and was especially significantly negatively correlated with the immune scores in Glioma." (PMID 35955624, 2022). "Although CHD5 exerts a broad tumor suppressor effect in many tumor types, its specific functions regarding its expression levels, and impact on immune cell infiltration, proliferation and migration in glioma remain unclear." (PMID 35955624, 2022). "Therefore, CHD5 may be a promising biomarker for glioma to predict patient prognosis and efficacy of anticancer therapy." (PMID 35955624, 2022). "Thus, based on its likely involvement as a tumor suppressor gene (TSG) in neuroblastomas, gliomas, and many common adult neoplasms, CHD5 may play an important developmental role in many other tissues besides the nervous system and testis." (PMID 29682202, 2018). "Thus, deletion of CHD5 has been proposed as an initiating event in gliomas." (PMID 20950435, 2010). "Forest plots indicated that the expression of CHD5 was significantly correlated with PFI in PRAD (p < 0.001), COAD (p = 0.02), COADREAD (p = 0.02), HNSC (p < 0.01), PCPG (p < 0.01), Glioma (p = 0.02), LGG (p = 0.03), and PAAD (p < 0.04) (Figure A3A)." (PMID 35955624, 2022). "In addition, we also observed that the expression of CHD5 in GBM was sex dependent (p < 0.05), and significantly differentially expressed (p = 0.04) during different stages of Glioma." (PMID 35955624, 2022). "We further detected a correlation between high CHD5 expression and lower DFI in MESO (p = 0.03) and COADREAD (p = 0.05), while in Glioma (p < 0.001), KIPAN (p < 0.001), PAAD (p < 0.01), KICH (p < 0.01) and LGG (p = 0.01), high CHD5 expression was correlated with a higher DFI (Figure A2A)." (PMID 35955624, 2022). "Recently, low levels of CHD5 expression have been reported in gliomas with 1p deletion, whereas nondeleted tumors displayed expression levels comparable to normal brain." (PMID 20950435, 2010).
hepatocellular carcinoma (10 papers, 2015 to 2026). A malignant tumor that arises from hepatocytes. "CHD5 is believed to serve as a master regulator in tumor-suppressive networks, and CHD5 expression levels are strongly associated with the prognosis of several cancers, including hepatocellular carcinoma and non-small cell lung cancer." (PMID 37521848, 2022). "One study found that a rare CHD5 variant, rs12564469-rs9434711, contributed to the risk of hepatocellular carcinoma, a risk effect which was statistically significant in alcohol drinkers but not smokers." (PMID 37521848, 2022). "In the present study, we demonstrated that reduced levels of CHD5 in hepatocellular carcinoma (HCC) tissues were significantly associated with metastasis and poor prognosis." (PMID 26517514, 2015). "The aim of this study was to determine whether CHD5 variants contribute to the risk of hepatocellular carcinoma (HCC)." (PMID 29907144, 2018). "By reviewing the literature, LC16A1-AS1 has been reported to enhance radiosensitivity and repress cell proliferation and invasion by regulating the miR-301b-3p/CHD5 axis in hepatocellular carcinoma and to suppress cell proliferation in cervical squamous cell carcinoma by the miR194/SOCS2 axis." (PMID 35372039, 2022).
lung carcinoma (8 papers, 2014 to 2023). "Taken together, these studies suggest that KDM4A promotes lung cancer progression by reducing the tumor suppressor CHD5 and activating related oncogenes." (PMID 37692513, 2023). "We found that except for CHD5, nearly all members of CHDs in lung cancer showed altered expression compared with adjacent normal tissues." (PMID 35467222, 2022). "In contrast, CHD5 has been reported as a tumor suppressor gene in some tumors, such as in lung cancer." (PMID 27955690, 2016). "Similarly, the expression level of CHD5 was upregulated in two subtypes of lung cancer, lung carcinoma (fold change = 8.841) and small cell lung carcinoma (fold change = 6.562)." (PMID 35467222, 2022). "In addition to ASCL2 gene, JMJD2A was shown to transcriptionally repress other genes, such as the tumor suppressor gene CHD5 in a lung carcinoma model." (PMID 24886710, 2014). "JMJD2A was reported to transcriptionally repress ASCL2 in vitro and CHD5 in lung carcinoma." (PMID 24886710, 2014). "Recent studies have demonstrated that CHD5 expression is epigenetically silenced by promoter DNA hypermethylation in HCC, colorectal cancer, breast cancer, gastric cancer, and lung cancer." (PMID 26517514, 2015). "Recently, it has been demonstrated that CHD5 promoter hypermethylation results in low or absent CHD5 protein levels in lung cancer and that elevated JMJD2A expression observed in lung tumors of both human and mouse could contribute to the reduction of CHD5 levels." (PMID 24454811, 2014).
breast carcinoma (7 papers, 2012 to 2025). "CHD5 loss-of-function or inactivation due to promoter hypermethylation, deletions and/or mutations has been reported in breast cancer pathogenesis." (PMID 41278204, 2025). "Although somatic mutation of CHD5 is rare, obvious down-regulation of CHD5 mRNA and protein was frequent in breast cancer cell lines and primary tumors." (PMID 22569290, 2012). "In the original study that identified 122 genes with somatic mutations in breast cancer through large-scale DNA sequencing, two of the 11 (18%) primary breast cancers had a heterozygous missense mutation in CHD5 (133G > A, V45M; 1999A > G, R667G)." (PMID 22569290, 2012). "Reduced CHD5 mRNA expression was significantly associated with lymph node metastasis, while reduced CHD5 protein expression significantly correlated to recurrence, distant metastasis, progression-free survival and overall survival in breast cancer." (PMID 22569290, 2012). "Whereas one mutation, a truncation mutation in the MDA-MB-231 breast cancer cell line, was found in CHD5 among the samples examined, CHD5 had frequent genomic deletion and promoter methylation in both breast cancer cell lines and primary tumors." (PMID 22569290, 2012). "We transfected MDA-MB-231 breast cancer cells, which have a truncation mutation of CHD5, with CHD5 expression plasmid or vector control." (PMID 22569290, 2012). "We examined CHD5 for somatic mutation, copy number changes, mRNA and protein expression, and promoter methylation in primary tumors and cell lines from human breast cancer." (PMID 22569290, 2012). "Sequencing the coding exons and adjacent splicing junctions of CHD5 in 38 primary tumors and 17 cell lines of breast cancer identified only one heterozygous frameshift mutation (3215delG) in the MDA-MB-231 cell line." (PMID 22569290, 2012). "Although only one mutation was detected, CHD5 mRNA expression was significantly reduced, accompanied by frequent genomic deletion and promoter methylation, in breast cancer." (PMID 22569290, 2012). "We previously reported the mutation spectra for CHD4 and CHD5 in TCGA breast cancers." (PMID 28649742, 2017). "In this manuscript, we found that promoter methylation, genomic deletion and down-regulation of CHD5 at both RNA and protein levels are common in breast cancer, and CHD5 down-regulation was significantly associated with metastasis and worse patient survival in breast cancer." (PMID 22569290, 2012). "The CHD5 locus at 1p36 is deleted, and its mutation has been detected in breast cancer." (PMID 22569290, 2012). "Furthermore, the only breast cancer cell line harboring a truncated mutation at CHD5, MDA-MB-231, is highly metastatic." (PMID 22569290, 2012). "In addition, in the highly metastatic MDA-MB-231 breast cancer cell line, which harbors a truncating mutation, ectopic expression of CHD5 suppressed cell proliferation in vitro and tumorigenesis in nude mice by arresting the cell cycle, and inhibited cell invasion." (PMID 22569290, 2012). "Given the methylation status of CHD5 gene in breast cancer patients found in TCGA, we aimed to characterize DNA methylation status at the CHD5 promoter." (PMID 29682202, 2018). "CHD5 protein expression was confirmed in six breast cancer cell lines and HMEC cells by Western blotting." (PMID 22569290, 2012). "CHD5 mRNA expression was determined in 32 cell lines and 58 primary tumors of breast cancer by real time PCR." (PMID 22569290, 2012). "In the T-47D breast cancer cell line, which expresses a high level of CHD5, we knocked down CHD5 expression by RNAi, and unexpectedly detected a significant decrease in cell proliferation." (PMID 22569290, 2012). "Down-regulation of CHD5, mediated at least in part by promoter methylation, contributes to the development and progression of human breast cancer." (PMID 22569290, 2012).
breast carcinoma (continued). "Changes in CHD5's copy number were determined in 29 breast cancer cell lines and 15 paired breast cancer tissues by real-time PCR with a pool of normal human genomic DNA as the control for normal genome." (PMID 22569290, 2012). "Functionally, ectopic expression of CHD5 in breast cancer cells inhibited cell proliferation and invasion in vitro and tumorigenesis in nude mice." (PMID 22569290, 2012). "Overall, these findings suggest that CHD5 expression might correlate directly with breast cancer survival." (PMID 41278204, 2025). "CHD5 is the most well-studied among the subfamily members for its role in breast cancer." (PMID 41278204, 2025). "Thus, we analyzed the methylation status along the CHD5 gene locus of 743 breast cancer patients and 98 normal samples obtained from TCGA (Ilumina Human Methylation 450 K) through the TCGA wanderer web service." (PMID 29682202, 2018). "We hypothesize that CHD5 is a tumor suppressor gene in breast cancer and tested this hypothesis in this study." (PMID 22569290, 2012). "Hemizygous deletion and promoter methylation were also common and could be responsible for transcriptional down-regulation of CHD5 in breast cancer." (PMID 22569290, 2012). "In this study, we conducted a series of studies to examine whether CHD5 is a tumor suppressor gene in human breast cancer." (PMID 22569290, 2012). "Our results strongly support a tumor suppressor role for CHD5 in breast cancer." (PMID 22569290, 2012). "Therefore, it is possible that inactivation of CHD5 contributes to metastatic progression of breast cancer." (PMID 22569290, 2012). "Interestingly, reduced CHD5 expression significantly correlated with lymph node metastasis, recurrence and shorter patient survival in breast cancer." (PMID 22569290, 2012). "In our study, none of the 38 primary tumors had somatic mutations in CHD5, while one of the 17 breast cancer cell lines examined had a frame shift mutation." (PMID 22569290, 2012). "Therefore, methylation-mediated silencing, which is a common mechanism for the inactivation of tumor suppressor genes, occurs at CHD5 in different types of human cancers including breast cancer." (PMID 22569290, 2012). "We, therefore, evaluated whether CHD5 plays a role in human breast cancer." (PMID 22569290, 2012). "Promoter hypermethylation correlated with lower levels of CHD5 mRNA expression, and demethylating treatment decreased promoter methylation and increased CHD5 expression, suggesting that promoter methylation is responsible at least in part for reduced CHD5 expression in breast cancer." (PMID 22569290, 2012). "Our results are consistent with another report in which no mutations were detected in 60 breast cancer samples while three mutations were identified in 123 ovarian cancer samples, indicating that, although mutation of CHD5 could occur in breast cancer, its frequency is rather low in primary tumors." (PMID 22569290, 2012). "Furthermore, knockdown of CHD5 in T-47D cells reduced the expression of the epithelial marker E-cadherin and increased the expression of mesenchymal marker vimentin, suggesting that CHD5 loss could induce EMT in CHD5-positive breast cancer cells." (PMID 22569290, 2012). "Consistent with the inhibition of invasion, CHD5 down-regulated mesenchymal markers vimentin, N-cadherin and ZEB1 in breast cancer cells." (PMID 22569290, 2012). "We noticed that in the T-47D breast cancer cell line, which expresses a higher level of CHD5, RNAi-mediated knockdown of CHD5 did not increase cell proliferation." (PMID 22569290, 2012).
breast carcinoma (continued). "CHD5 protein expression was also reduced in breast cancer, and lack of CHD5 expression significantly correlated with higher tumor stage, ER/PR-negativity, HER2 positivity, distant metastasis and worse patient survival (P ≤ 0.01)." (PMID 22569290, 2012). "In the breast cancer tissues, while 145 (50.2%) tumors showed various levels of CHD5 protein expression, 144 of them (49.8%) showed no obvious CHD5 expression." (PMID 22569290, 2012). "Analysis of TCGA datasets show that the CHD5 promoter region is not methylated in breast cancer patients, which suggests that another epigenetic mechanism could be involved in gene repression." (PMID 29682202, 2018). "However, whereas 1p36 is commonly deleted in human breast cancers, the role of CHD5 in breast cancer has not been evaluated." (PMID 22569290, 2012). "Hence, these datasets point out that DNA methylation at the promoter region is not related with CHD5 gene silencing, suggesting that there may be other mechanisms related to its repression in breast cancer." (PMID 29682202, 2018).